RETN (resistin)
Diseases named in the same sentence as RETN in open-access papers (continued):
Sharing a sentence is not in itself a finding about the gene and the disease.
Obesity (continued). "Hence, no definitive conclusions could be drawn regarding the effect of obesity or sex on circulating resistin concentrations in cats." (PMID 31533709, 2019). "However, obesity provokes a Th1 response, initiated by hypertrophic adipocytes secreting inflammatory adipokines like leptin, resistin, and angiotensin II as well as generating so-called damage-associated molecular patterns (DAMPs) by necrotic cell death and lipids associated with lipotoxicity." (PMID 31349725, 2019). "As resistin is an adipokine which has been shown to interfere with intracellular insulin signalling, and also stimulates monocyte and macrophage inflammatory cytokine production, this may contribute to the systemic low-grade inflammation observed in obesity." (PMID 30261617, 2018). "Thus, obesity may promote the occurrence of asthma and further aggravate asthma by promoting the increase of resistin." (PMID 30050954, 2018). "Moreover, both MeS and obesity are characterized by the activation of several inflammatory pathways, including cytokines as Interleukin-6, Tumor Necrosis Factor-alpha, Interleukin-1 and adipokines as leptin, adiponectin and resistin." (PMID 29112985, 2017). "Therefore, obesity may be connected to the pathogenesis of endocrine disease via specific predicted genes, such as RETN." (PMID 29258237, 2017). "Resistin was named due to its ability to modulate insulin resistance, but studies of resistin associations with clinical parameters of metabolic disease have shown both positive and negative correlations with obesity, insulin resistance, and other metabolic parameters." (PMID 28413567, 2017). "Recent studies suggest that adipocyte-derived secretory factors including adiponectin, leptin, resistin, visfatin, and numerous cytokines including TNF-alpha, IL-6, and IL-10 may be the key to link obesity with CRC, although underlying mechanisms remain unexplained." (PMID 27642602, 2016). "This suggests resistin could be a biochemical link between obesity related inflammation and cancer." (PMID 27314854, 2016). "Presumably resistin might represent a link between obesity, insulin resistance and diabetes." (PMID 25129652, 2015). "The effects of resistin on stroke risk could not be explained by the obesity-associated pathways and might involve additional unidentified biological mechanisms." (PMID 26783391, 2015). "Given our discussion above on the importance of the renal sympathetic nerve responses in the potential for leptin to contribute to obesity-induced hypertension, the similar sympatho-excitatory actions of resistin and leptin on renal sympathetic nerve activity could assume greater significance." (PMID 26617526, 2015). "Nonetheless, as both resistin and leptin are elevated in obesity, and they each have sympatho-excitatory actions on renal and lumbar sympathetic nerve activity, it is quite possible that the effects on those outputs is exacerbated when leptin and resistin are present together." (PMID 26617526, 2015). "Aiming to explore a potential link between irisin and obesity in human breast malignancy, we investigated potential correlations of irisin levels with body mass index (BMI) and with levels of the adipokines leptin, adiponectin and resistin in breast cancer patients." (PMID 26560078, 2015). "Thus, we hypothesize that leptin and resistin, when present in high concentrations, may act together and contribute to obesity-induced hypertension and renal dysfunction." (PMID 26617526, 2015). "Thus resistin would be one of the molecular links connecting obesity, periodontitis, and diabetes and may serve as a marker that links periodontal disease with other systemic diseases." (PMID 24692844, 2014). "Moreover, authors reported increased resistin levels in association with obesity and IR in T2D, whereas other study observed no change in resistin levels under such conditions." (PMID 25551102, 2014).
Obesity (continued). "However, in humans, resistin has not been associated with insulin resistance or obesity and the determination of resistin as a marker of insulin resistance in children is not recommended." (PMID 25541889, 2014). "Hence, they may be involved in the pathogenesis of obesity and the role of some of them (leptin, adiponectin, resistin, and visfatin) has been extensively studied in the disease." (PMID 24376307, 2013). "Furthermore, one metabolically active hormone is resistin, which is secreted by adipocytes and may contribute to obesity, insulin resistance, and diabetes in mice." (PMID 24302970, 2013). "Serum resistin was initially hypothesized as a link between obesity and insulin resistance in mice." (PMID 22969799, 2012). "Thus, resistin may perform an intermediary role between obesity and insulin resistance in rodents although this role is still questioned in humans." (PMID 22645452, 2012). "Therefore, resistin levels in saliva may be used as a tool to evaluate inflammation/obesity/insulin resistance state for T2DM patients." (PMID 22969799, 2012). "Thus, resistin is a hormone that potentially links obesity with diabetes." (PMID 21686173, 2011). "However, the observed positive correlation ofcirculating resistin with BMI and waist circumference might support someassociation of resistin with obesity-induced insulin resistance." (PMID 19125180, 2008). "In a recent study,the expression of two adipokines, resistin, and visfatin was detectedpredominantly in the macrophages populating the human visceral fat tissue,suggesting that these adipokines might have an important role in theinflammatory load of obesity." (PMID 19125180, 2008). "Hence, resistin has been proposed as a link between obesity, insulin resistance, and hyperglycemia." (PMID 16854242, 2006). "Elevated pro-inflammatory mediators in obesity, including TNF-α, leptin, and resistin, disrupt cellular glucose uptake via suppression of insulin receptor signaling, culminating in hyperglycemia and diabetes." (PMID 41246338, 2025). "Notably, elevated plasma resistin levels have been strongly correlated with systemic inflammation and insulin resistance in rodents and humans, reinforcing the hypothesis that resistin may be a molecular link between obesity and metabolic dysfunction." (PMID 40759954, 2025). "In obesity, excess adipose tissue and increased production of adipokines—such as tumor necrosis factor-alpha (TNF-α), various interleukins, and resistin—trigger a state of chronic inflammation." (PMID 40283140, 2025). "Median TMAO levels rose from 122.00 in the Normal weight group to 254.00 in the Obesity III group (p < 0.001), while resistin levels increased from 5.50 to 9.00 (p = 0.001)." (PMID 40077669, 2025). "Despite these findings, limitations remain in assessing TMAO, resistin, and CIMT in individuals with obesity, warranting further investigation." (PMID 40077669, 2025). "Obesity, small dense LDL-cholesterol, and resistin interact in a complex web of physical dysfunctions that are greatly influenced by the interrelated roles of aging, gender, and other illnesses." (PMID 41315571, 2025). "Due to the subclinical inflammation condition (characteristic of obesity), the higher MCP-1 and resistin make proper sense." (PMID 40565251, 2025). "Obesity promotes a pro-inflammatory environment by increasing TNF-α, IL-6, IL-1, leptin, and resistin levels that reach the bloodstream and generate a systemic inflammatory state." (PMID 40067600, 2025). "There were a total of nine positive factors, namely, obesity, BMI, body fat percentage, waist circumference, hip circumference, HDL cholesterol, apoA1, resistin, and NGF." (PMID 39050546, 2024).
Obesity (continued). "In the group of women with obesity compared to those with normal body weight, significantly higher serum levels were found for IL-6, MMP-2, and resistin." (PMID 39769504, 2024). "Clinical studies have demonstrated higher resistin (hyper-resistinemia) levels in individuals with T2DM and obesity." (PMID 39335642, 2024). "Although the pathogenesis of metabolic syndrome and its links to obesity are not fully understood, it is thought that adipocytokines such as adiponectin, tumour necrosis factor-α (TNF-α), and resistin play a key role." (PMID 38202263, 2024). "Because of the impact of obesity on the development of CRC and the role of resistin in insulin resistance, research has focused extensively on measuring resistin levels in CRC patients." (PMID 39184804, 2024). "In contrast, in WAT dysfunction in obesity, pro-atherogenic factors, such as FFAs, TNF-α, IL-6, resistin, and leptin, are secreted, which increase the development of atherosclerosis, internal plaque inflammation, and plaque vulnerability." (PMID 38051471, 2024). "Resistin and MMP-2 were significantly different between women with obesity and women with normal body weight." (PMID 39769504, 2024). "In pregnant women, both obesity and diabetes increase pro-inflammatory cytokines and adipokines, such as TNF-α, IL-6, IL-1β, leptin, and resistin, which are involved in the inflammatory response." (PMID 39584800, 2024). "The development of obesity in mice fed WD was also reflected by the significantly increased plasma levels of the hormones leptin, peptide YY (PYY), resistin, and glucose-dependent insulinotropic polypeptide (GIP)." (PMID 38469142, 2024). "Our study indicated the effectiveness of SW20.1, an ATF3 expression inducer, in reducing and preventing obesity and its related metabolic disorder through the ATF3–resistin pathway." (PMID 37371606, 2023). "Initially, resistin was believed to promote insulin resistance, T2DM, and obesity by inducing lipolysis in adipocytes." (PMID 37834128, 2023). "To conclude, the adipokines adiponectin, leptin, resistin, IL-6, MCP-1 and PAI-1 produced by the adipose tissue are deregulated in the context of obesity." (PMID 38136564, 2023). "Furthermore, U0126 treatment was found to reverse the inhibitory effect of central resistin on thermogenesis, and U0126 was also shown to regulate thermogenesis induced by Baicalin, a flavone compound extracted from plant roots, thus potentially counteracting diet-induced obesity." (PMID 37175694, 2023). "There is still a lack of data concerning the impact of indole derivatives on the modulation of adiponectin, leptin, resistin and PAI-1 production in adipose tissue during obesity." (PMID 38136564, 2023). "In obesity, various adipocyte-derived pro-inflammatory cytokines, including TNF-α, interleukin-1β, interleukin-6, monocyte chemotactic protein-1, leptin, and resistin are overproduced, contributing to IR." (PMID 37503477, 2023). "Pregnant women with obesity and diabetes often have an increase in pro-inflammatory cytokines and adipokines, such as TNF-α, IL-6, IL-1β, leptin, and resistin, which are involved in the inflammatory response." (PMID 37515062, 2023). "We also observed the decreased expression of adiponectin and resistin in the HFD-fed mice, supporting the onset of obesity and corroborating the results of a previous study." (PMID 37334370, 2023). "Interestingly, our findings contribute to the data in the context of obesity and bariatric surgery, as they demonstrated that over time, resistin levels significantly increased in patients in the CG, which may indicate a worsening of their condition leading to adverse consequences." (PMID 36788619, 2023). "Our results provide evidence demonstrating a significantly higher serum level of resistin in patients with COPD concomitant with sarcopenia and obesity compared with that in patients with concurrent obesity or sarcopenia only." (PMID 37853348, 2023).
Obesity (continued). "Previous studies show positive correlations between Leptin, Visfatin, Resistin and Adipsin and circulating inflammatory markers such as IL-6 and CRP in individuals suffering from obesity." (PMID 35684160, 2022). "Unlike leptin, there were no significant changes of the systemic levels of adiponectin, resistin, and progranulin, which has recently been shown to correlate positively with CTRP-3 serum levels in obesity." (PMID 33562308, 2021). "Macrophage migration in patients with obesity infiltrates into the vicinity of fat cells, leading to the secretion of inflammatory cytokines, thereby upregulating the expression of TNF-α and resistin." (PMID 34283904, 2021). "In our study, we saw a significant increase in the expression of TNF-α, resistin, and IL-10 by adipocytes isolated from ING and RP depots, as a consequence of the HF diet-induced obesity." (PMID 33652751, 2021). "They found that both the expression level of leptin and resistin were significantly increased in the HFD group treated with DOX, confirming obesity conditions induced the changes in tissue fatty acid composition to further reduce the therapeutic effect of DOX." (PMID 34350120, 2021). "The serum levels of adipokines, leptin and resistin, were increased by the consumption of HFD as the mice developed obesity." (PMID 33535476, 2021). "This biomarker panel is used to diagnose obesity-related NASH based on adiponectin, cleaved cytokeratin 18 (CK-18) M30, and resistin levels." (PMID 35096868, 2021). "However, in pathological conditions such as obesity, dysfunctional adipocytes mostly produce and release pro-inflammatory adipokines such as leptin, tumour necrosis factor-α (TNFα), interleukin 6 (IL-6), interleukin 18 (IL-18), or resistin, which have atherogenic effects." (PMID 33081064, 2020). "As obesity progresses, proinflammatory adipokines, including leptin, TNF, resistin, IL-6, RBP4, lipocalin-2, and ANGPTL-2, are preferentially synthesized and cause chronic inflammation." (PMID 33133214, 2020). "Resistin influences insulin homeostasis, but the relationship between its serum levels and DM2, insulin resistance, or obesity is unclear and an increase in resistin levels correlated with these pathologies is still questionable." (PMID 33182462, 2020). "This obesity-induced inflammation will elevate the level of C-reactive protein, ICAM, and resistin, which subsequently increases the level of cholesterol in the blood." (PMID 33029159, 2020). "We believe this is the first study in the evaluation of the serum concentrations of resistin in female dogs with CBMT and its relationship with the proliferative potential, obesity, and survival." (PMID 32903534, 2020). "Finally, a possible role of resistin might be considered as a new link between obesity and diabetes, since resistin levels are increased in diet-induced obesity, as well as in genetic models of obesity and IR, and its inhibition enhanced insulin-stimulated glucose uptake." (PMID 33142938, 2020). "In our study, increased levels of resistin, TNF-α, IL-1β, and IL-6 were observed in the spleen in DIO mice, which suggested that the changes of cytokine in the spleen in obesity were indicative of altered immune functions." (PMID 32104715, 2020). "Galantamine treatment of mice with established obesity (after 8 weeks on a high-fat diet) significantly lowers plasma IL-6, CCL2, leptin, and resistin levels, and reduces body weight, food intake, and abdominal white adipose depots." (PMID 31024226, 2019). "We found resistin levels were weakly correlated with insulin resistance in those with T2DM and obesity (r = 0.21, 95% CI: 0.06–0.35, I2 = 59.7%, P = 0.003)." (PMID 31803062, 2019). "Studies on levels of resistin in PWS subject are scarce, but a significantly higher resistin concentration was reported in PWS patients in comparison with both healthy lean subjects and subjects with obesity." (PMID 29371863, 2018).
Obesity (continued). "Resistin levels were normal or decreased, which is in contrast to earlier reported data in PWS patients and to studies in simple obesity, where resistin levels are known to be elevated." (PMID 29371863, 2018). "To unravel the mechanism as to how obesity impairs the outcome of DTIC therapy in melanoma, we investigated the specific role of leptin and resistin as their levels in serum are elevated under obese condition." (PMID 29568521, 2018). "Additionally, once obesity develops, insulin resistance and metabolic inflammation due to the dysfunction of adipocytokine secretion, which includes increased tumor necrosis factor-α and resistin as well as a decreased adiponectin, are triggered and result in metabolic dysfunction." (PMID 30537972, 2018). "Since the discovery of resistin, many studies mainly focused on the relationship among it with insulin resistance and obesity, and suggested that resistin may be an important factor which can lead to obesity, insulin resistance and type 2 diabetes mellitus (T2DM)." (PMID 28404934, 2017). "Adipose tissue (AT) has a modulating role in obesity-induced metabolic complications like type 2 diabetes mellitus (T2DM) via the production of so-called adipokines such as leptin, adiponectin, and resistin." (PMID 28686216, 2017). "Taking into account the opposite effects of adiponectin and resistin, it was suggested that the interplay between these two adipokines may determine the metabolic profile of obese individuals and, possibly, be responsible for the development of obesity-related complications." (PMID 29213336, 2017). "Serum resistin levels may be an independent risk of obesity-related cancers, but not a predictor." (PMID 27509174, 2016). "For several adipokines (ANGPTL3, DLL1, chemerin, clusterin, leptin, Nampt, resistin, GPX3), we identified a close relationship with parameters of obesity (BMI, waist circumference, body fat mass), but also inflammation (hsCrP)." (PMID 24968098, 2014). "Resistin, known as adipocyte-secreted factor (ADSF) or found in inflammatory zone 3 (FIZZ3), was discovered in 2001 and was proposed as potential link between obesity and diabetes." (PMID 22910888, 2012). "NSPT effectively improved clinical periodontal health and reduced salivary resistin levels in individuals with periodontitis, regardless of obesity status." (PMID 41602238, 2026). "NSPT effectively improved periodontal health and lowered salivary resistin levels in individuals with periodontitis, regardless of obesity status." (PMID 41602238, 2026). "Biomarkers, such as ferritin, leptin, resistin, interleukin-6 (IL-6), insulin, tumor necrosis factor-alpha and plasminogen activator inhibitor-1 (PAI-1), play crucial roles in the pathophysiology of obesity." (PMID 41011232, 2025). "Furthermore, emerging evidence indicates that gut bacteria-derived metabolites upregulate the production of pro-obesity adipokines, such as leptin, resistin, IL-6, MCP-1, and PAI-1, and downregulate the anti-obesity ones, such as adiponectin." (PMID 40699823, 2025). "HFD led to greater body weight, serum cholesterol, glucose, and elevated levels of pro-inflammatory cytokines and adipokines, such as leptin, resistin, PCSK9, and DPPIV/CD26, consistent with findings that obesity drives chronic inflammation and metabolic dysregulation." (PMID 40998975, 2025). "Considering that resistin is effective in increasing insulin resistance and SREBP-1c in increasing lipogenesis, it can be concluded that these correlations are important in the development of obesity." (PMID 41417360, 2025). "We determined the circulating concentrations of adiponectin, leptin, resistin, TNFα, and IL-6 in participants with obesity and type 2 diabetes with and without obesity, and compared them to those of the control group." (PMID 40095937, 2025).